IL1B (interleukin 1 beta)
Diseases named in the same sentence as IL1B in open-access papers (continued):
Sharing a sentence is not in itself a finding about the gene and the disease.
tumor (continued). "Tocilizumab, an IL-6R antibody, could induce the production of tumor immunity-stimulating factors, such as IL-12, IL-1β, and anti-tumor cytokines, such as TNF-α, and IFN-γ." (PMID 35681617, 2022). "We report six conserved meta-programs that distinguish tumor cell function, and find an epithelial-mesenchymal transition meta-program highly enriched at the tumor-normal interface that co-localizes with IL1B-expressing macrophages, offering a potential therapeutic target." (PMID 36423636, 2022). "Like IL-1β, IL-18 exhibits a dual-role in tumor development by regulating the TIME." (PMID 35739593, 2022). "-Ileal microbiota is critical for the activation of TFH cells-The density of TFH cells correlated with ileal caspase-3 activation during ileal apoptosis, suggesting a potential anti-tumor activity-Microbial structures such as bacterial RNA can trigger IL-1β-dependent differentiation of TFH cells." (PMID 35565269, 2022). "Additionally, regulatory T cell (Treg) tumor infiltration was reduced, which was due to the loss of AIM2-dependent production of IL-1β and IL-18." (PMID 35432377, 2022). "In contrast, IL1β appears to play a tumour-supporting function in the bone, and it has previously been demonstrated that IL1β controls myeloid cell number, reduces recruitment of anti-tumour neutrophils to bone and drives mobilisation of immune cells out of the bone marrow." (PMID 36230739, 2022). "IL-1β is thought to facilitate tumor growth, angiogenesis, and metastasis in PDAC and may therefore negatively influence patient prognosis." (PMID 36091056, 2022). "Both IL-1α and IL-1β stimulated tumor-induced osteoclastogenesis." (PMID 36614130, 2022). "Flow cytometry analysis demonstrated robust expression of NLRP3 and pro-IL-1β in MDSCs from spleens of naïve mice as well as in highly pure MDSCs isolated from tumor-bearing mice, and this is accompanied by increased levels of secreted IL-1β as determined in culture supernatants." (PMID 36032139, 2022). "In melanoma, high levels of IL-37 expressed by peripheral Tregs were found to mirror the secretion of IL-1β mediators, especially TGFβ, by the tumor, suggesting it could be used as a possible biomarker for tumor-induced immunosuppression." (PMID 36551790, 2022). "In line with IL1β inhibition holding tumours in a dormant state, we found that inhibition of IL1 was effective in reducing bone metastasis or delaying the development of bone metastasis; however, once overt metastases had developed, IL-1 inhibitors were no longer able to reduce tumour growth." (PMID 36230739, 2022). "Tumor-associated macrophages (TAM), myeloid-derived stem cells (MDSC), and lymphocytes Th1/Tc infiltrating the TME influence the epithelial cells undergoing TME through the secretion of IL-1β, IL6, IL8, IL10, IL17, TGF-β, or TNFα." (PMID 35884974, 2022). "As for IL-1β, IL-18 is an essential inducer of anti-tumor immunity." (PMID 35517498, 2022). "IL-1β can be triggered by inflammatory signaling in multiple immune types and is an important factor and driver of tumor malignant evolution, therefore IL-1β blockade may be an important strategy to inhibit tumor growth and metastasis." (PMID 35701840, 2022). "Additionally, the administration of berberine is capable of inhibiting the growth of tumor cells and decreasing the expression of IL-1β and caspase-1." (PMID 36144625, 2022). "Macrophages-IL1B in high tumor cell infiltration group exhibited enhanced lipid metabolism and weakened oxidative phosphorylation, glycolysis/gluconeogenesis, citrate cycle (TCA cycle) and amino acid metabolism compared to the corresponding sub-clusters in low tumor cell infiltration group." (PMID 36532059, 2022). "As MLL-tumors express high levels of IL6, IL1β and TNFα9, changes in the liver could be related to a tumor-induced acute phase response." (PMID 35551231, 2022).
tumor (continued). "Favorable, anti-inflammatory cytokines, such as IL-1RA, IL-7, and MIP-1β were detected in higher concentrations in responding patients, while pro-inflammatory, tumor-promoting cytokines, such as IL-18 and IL-1β, were higher in patients with early progressive disease." (PMID 36091056, 2022). "In addition, transgenic mice null for IL1R and grafted with PC3-ML cells developed significantly fewer and smaller skeletal lesions, suggesting IL1β secretion in the bone stroma forms a tumor-permissive niche." (PMID 36561929, 2022). "The recruitment of myeloid cells is one of the pro-tumoral activities exercised by IL-1β, whose neutralization by an anti-IL-1 receptor (IL-1R) antibody curbed myeloid cell accumulation and tumor progression in mouse models of lung, breast and pancreatic tumors." (PMID 35158779, 2022). "IL-1β was also found to regulate the expression of tumor-related genes in the bone stroma." (PMID 36237303, 2022). "Additionally, the NF-kB-inducing cytokines TNF, TL1A and IL-1β all promote Th9 cell differentiation and specifically enhance the anti-tumor efficacy of Th9 adoptive cellular therapy (ACT)." (PMID 36389679, 2022). "Furthermore, PD‐L1 expression is enhanced by TNF‐α and IL‐1β, suggesting that the expression of PD‐L1 in tumor cells changes depending on the tumor microenvironment." (PMID 34842351, 2022). "Luminex-based multi-cytokine analysis in the peripheral blood of tumor-bearing mice on day 35 demonstrated elevated levels of inflammatory cytokines (IFNγ, IL-1β, TNFα and Il-17) in the HS diet cohort, while there were elevated anti-inflammatory IL-10 blood levels in the LS diet cohort." (PMID 35741331, 2022). "Normal and tumor cells released low levels of IL-1β and IL-10." (PMID 35335367, 2022). "Thus, our study indicates that harboring ARNEG cancer cells and/or being treated with ADT/ARIs increase tumor-derived IL1β which—upon its secretion—can instigate a stromal niche favorable to further tumor growth." (PMID 36561929, 2022). "The effects of IL-1β on angiogenesis in the tumor microenvironment have been described." (PMID 36324671, 2022). "IL-6 was highly expressed in the tumor microenvironment; it could enhance the secretion of IL-1β and IL-18 and trigger the inflammatory storm in vivo." (PMID 35464414, 2022). "Since IL-1β is known to promote MMP-9 production in tumor cells, ILC2 may instigate ECM remodeling by PMN-MDSC activation during the early stages of metastasis." (PMID 35805039, 2022). "However, corylin inhibited the mRNA expression and protein levels of Ifnγ, Tnf-α, Il-6, Il-1β, Nlrp3, Asc, Pannexin, and Pro-caspase 1 in the tumor tissues of AOM/DSS-induced CAC mice." (PMID 35269806, 2022). "In transplantation tumor models, IL1β has been shown to be required for cross-priming CD8+ T cells." (PMID 36077828, 2022). "The prolonged inflammatory effects of IL-1β are counterbalanced by the action of the interleukin-1 receptor antagonist (IL-1RA) cytokine that competitively inhibits the binding of circulating IL-1β during an inflammatory event to quench acute inflammation and avoid tumor angiogenesis/metastasis." (PMID 36432658, 2022). "Other biologicals such as a monoclonal antibody against IL1b (canakinumab) might restore cytotoxic T-cell function in tumors, thus reducing pro-tumor inflammation." (PMID 35203471, 2022). "IL-1β was reported to induce Th1 and Th17 to strengthen the anti-tumor effect." (PMID 36237303, 2022). "IL-1β is a key mediator of inflammation and immunity, contributing to tumor invasiveness and metastasis via the expression of various genes for arranging the tumor microenvironment." (PMID 36445856, 2022). "Inflammatory cytokines, such as TNF-α, IL-1β, and IL-6, are also found in tumor biopsy samples." (PMID 34194957, 2021). "However, some studies show that elevated expression of IL-1β would contribute to chronic inflammation that promotes tumour development and immunosuppression." (PMID 33918087, 2021).
tumor (continued). "However, appropriate analyses seem to be advisable, since inflammation is an important component of tumor progression, and elevated plasma levels of IL-1β have been found in patients with both small cell lung cancer and NSCLC." (PMID 34205482, 2021). "Accordingly, we detected strong expression of IL-1β and other inflammatory cytokines such as tumor necrosis factor (TNF) in SCC VII and 4T1 tumors (which include macrophages) grown in mice, but barely in the underlying tumor cells." (PMID 34876407, 2021). "The definitive functions of the NLRP3 inflammasome in mammary malignancy are still unknown, but several studies have demonstrated the pivotal function of IL-1β in tumorigenesis and neoplasm growth." (PMID 34064909, 2021). "IL-1β has been shown to be significantly upregulated in most primary tumors such as breast, prostate, colon, lung, head and neck cancer, and melanoma and promotes tumor cell migration, angiogenesis, immune response, and metastasis formation." (PMID 34064859, 2021). "Whether IL1β-mRNA elicits migration activity in ZC3H12D+NK cells because those cells migrated from the liver to the lungs in tumor-bearing mice was investigated." (PMID 34135341, 2021). "Downstream of inflammasome and GSDMD activation, IL-1β and IL-18 can also have a beneficial effect as they play a pivotal role in the activation of dendritic and natural killer (NK) cells, respectively, and can, thereby, promote anti-tumor immune responses." (PMID 34490126, 2021). "Since MSU is known to serve as a potent activator of the NLRP3 inflammasome, facilitating the synthesis of IL-1β and other inflammatory mediators, we assumed that inflammasome activation in the tumor environment controls the trafficking of excessively aging neutrophils to malignant tumors." (PMID 34876407, 2021). "Notably, RA alone was shown to inhibit inflammation in H22 tumor-bearing mice by reducing the IL-1β, IL-6, and TNF-α levels and p65 and p-p65 expression." (PMID 34833849, 2021). "Consequently, tumor cell-derived IL-1β has been identified as a potential biomarker for predicting the risk of developing bone metastases in patients with BrCa and is an emerging therapeutic target in bone-homing malignancies." (PMID 34064859, 2021). "In this model, IL-1B signalling is only active in tumour cells." (PMID 34290237, 2021). "Another potential mechanism by which increased tumor cell death is observed in our study could be the increase in the secretion of pro-inflammatory cytokines, such as IL-1β, which was previously shown to induce tumor cell death in the presence of IFN-γ." (PMID 33747968, 2021). "Surprisingly, IL-1β, a profound inducer of TF expression in endothelial cells and monocytes, has not yet been investigated in detail with regard to the molecular mechanisms of a corresponding regulation in tumor cells." (PMID 34205482, 2021). "Indeed, many of the described pro-tumorigenic properties of NLRP3 have been attributed to its role in driving the expression of IL-1β by tumor-infiltrating myeloid cells." (PMID 34638239, 2021). "Our finding suggested that cytokines such as IL-1α, IL-1β has been transcriptionally increased in which it may subsequently be secreted and promote an inflamed tumor microenvironment." (PMID 34789798, 2021). "More significantly, our finding revealed that DPP-4i also triggered NF-кB-dependent NLRP3 inflammasome activation, leading to caspase-1-mediated processing of IL-1β and IL-33, two critical proinflammatory cytokines for the tumor-immune-suppressive microenvironment." (PMID 34631556, 2021). "The increase of IL-1β/Arg1 and iNOS/Arg1 ratio confirms that modified exosomes derived from plasmid DNA transfected Panc-1 cells facilitate the macrophage remolding from M2 phenotype back to M1 type, leading to suppression of tumor progression." (PMID 34722637, 2021).
tumor (continued). "Cancer cell-derived extracellular vesicles (EVs) can modify the prostate microenvironment to promote cancer proliferation and can promote the activation of the NLRP3 inflammasome and caspase-1 and IL-1β release, contributing to the maintenance of proinflammatory tumor conditions." (PMID 34064909, 2021). "In agreement with our hypothesis that tumour-derived IL-1B drives an anti-tumour response, we quantified the infiltration of neutrophils in primary tumours and found a tendency for an increase in MPO+ neutrophils." (PMID 34290237, 2021). "On the other side, pyroptosis and IL1β production activate multiple signaling pathways and inflammatory mediators that promote tumor growth and metastasis in cancer models, triggering TAMs to boost tumor angiogenesis." (PMID 34447383, 2021). "In addition, CAFs are able to sense DAMPs, which ultimately activate the inflammasome to promote IL-1β production, which fuels BrCa tumor growth and metastasis." (PMID 34064859, 2021). "Furthermore, to determine the tumoricidal effects of B220+CD11c+NK1.1+NK cells, rhodamine-labeled E0771 cells were cocultured with IL1β-mRNA-primed NK cells to count dead tumor cells stained with Zombie, a green fluorescent dye." (PMID 34135341, 2021). "Also, IL-1β has been identified as one of the key node genes in the tumor microenvironment during oral carcinogenesis." (PMID 35048001, 2021). "Further systematic investigation on the change in tumor and stromal cells upon IL-1β neutralization in vivo may be able to illustrate the overall effect of IL-1β on PAAD progression." (PMID 34150748, 2021). "Thus, in this study we exposed TNBC cells to a persistent stimulation by TNFα + IL-1β together and determined the effects of this stimulatory setup on tumor cell phenotypes and activities." (PMID 34072893, 2021). "We propose that general inhibitors of inflammation such as NSAIDs or inhibitors of specific pro-inflammatory cytokines such as TNFα and IL-1β—that are constantly present at the tumor site from the time of malignant transformation and onwards—should be considered for the treatment of BC patients." (PMID 33806906, 2021). "Moreover, in tumor-naive mice, a single dose of anakinra was able to reduce osteoclast and osteoblast activity, as well IL-1β expression." (PMID 33840390, 2021). "We and others have previously shown that tumour-derived IL-1B drives EMT11,14." (PMID 34290237, 2021). "In particular, these authors observed that IL1β secreted by cancer-associated macrophages induced the secretion of CXCR2 ligands by CAFs, such as IL8 and GROα (CXCL1), which were ultimately the mediators of such tolerance in tumor cells." (PMID 34066976, 2021). "This study suggested that cryosurgery generates the most favourable immune-regulatory response for abscopal tumours and activation of anti-tumour immune cells, and increased secretion of pro-inflammatory cytokines such as IL-1β, IL-2, IL-6, IL-12β, IFN-γ and TNF-α." (PMID 34281259, 2021). "However, the mRNA abundances of the pro-inflammatory cytokines IL-6, MIP-1α, and IL-1β were specifically reduced in the non-tumour liver of PI3Kγ-/- mice compared with WT mice." (PMID 34704005, 2021). "Additionally, IL-1β was found to promote the recruitment of MDSCs and macrophages via chemokine expression and tumour cell arrest on endothelial cells via E-selectin expression in the PMN." (PMID 35006432, 2021). "We next studied the effects of IL-1β in the tumor colonization model." (PMID 34257370, 2021). "In the current study, we investigate how IL-1B from different environments influences immune cell abundance, driving primary tumour growth and bone metastasis and whether this has an effect on the response to standard of care therapies." (PMID 34290237, 2021). "Overexpression of IL-1β leads to enhanced metastasis (one of the major causes of adverse prognosis in patients with advanced OSCC) through secretion of oncogenic cytokines IL-6, IL-8, and GRO-α (growth-regulated oncogene α) by tumor cells." (PMID 34442627, 2021).
tumor (continued). "DOX administration reduced tumor-induced upregulation of IL-1β and TNF-α." (PMID 34445729, 2021). "In WZB117-treated animals, we noted an increase in expression of IL1β and other pro-inflammatory cytokines despite the attenuation of tumor burden, suggesting that the induction of anti-tumor CTL and NK immunity was sufficient to overcome this apparent increase in macrophage inflammation." (PMID 34198548, 2021). "Based on our results that IL1β expressed preferentially in a group of tumours showing strong TXNIP nuclear expression in supporting endothelial cells indicates that the IL1β expression is mediated through the NFkB pathway, rather than direct activation of NLRP3 inflammasome." (PMID 34433833, 2021). "IL-1β is identified as a key node gene in the tumor microenvironment (TME) of OSCC in vivo." (PMID 35048046, 2021). "Neutralization of IL-1β abolished the effect of IFI16-overexpressing tumor cells on TAMs." (PMID 34150748, 2021). "Indeed, studies have implicated the NLRP3-mediated release of IL-1β in the induction of the IL-22 cytokine by CD4+ T cells, a process observed to support tumor cell proliferation and growth." (PMID 34638239, 2021). "We next measured spontaneous production of IL-6 and IL-1β in ex vivo cultured bone marrow and spleen cells to determine whether tumor growth influenced host inflammatory responses." (PMID 33649199, 2021). "Moreover, fisetin exerted anti-inflammatory effects through the suppression of the NF-κB and ERK1/2 signaling pathways in IL-1β-stimulated A549 cells, suggesting to prevent tumor promotion." (PMID 34950252, 2021). "Therefore, we quantified macrophages and neutrophils in primary tumours overexpressing IL-1B from IL-1Bfl/fl and IL-1B−/− mice using IHC." (PMID 34290237, 2021). "IL-1β is one of the critical pro-inflammatory cytokines involved in tumor pathogenesis." (PMID 34211462, 2021). "IL-1β increases tumor infiltration of immunosuppressive macrophages and myeloid-derived suppressor cells (MDSCs), thereby promoting immune evasion, neoangiogenesis and tumor development." (PMID 34064909, 2021). "IL-1β and IL-6 participate in inducing IL-8 expression in polymorphonuclear leukocytes (PMNs), which in turn enable the extravasation of MCs.TANs are neutrophils engaged at tumor site and can be anti-or pro-tumor phenotypes, N1-TANs and N2-TANs, respectively." (PMID 35011682, 2021). "Moreover, neutrophils played a role in disrupting endothelial barriers by secreting Interleukin 1-β (Il-1β), promoting thus extravasation of tumour cells." (PMID 34241735, 2021). "Future studies on the detailed investigation of the relation of stromal secreted IL-6 and IL1B in BMDCs involvement in tumor invasion will be of great interest for clinical application in the preoperative assessment of the cancer aggressiveness and anti-cancer therapies." (PMID 35008304, 2021). "Knocking down ELF3 expression attenuates activation of NF-κB pathway genes in two LUAD cell lines A549 (KRAS mutation) and NCI-H1975 (EGFR mutation L858R), supporting the conclusion that inflammatory cytokines (e.g. IL1B) can regulate tumor cell proliferation and anti-apoptosis through ELF3 action." (PMID 33144684, 2021). "Thus, blocking the action of IL1β disrupted the migratory capabilities of tumor cells and restored the myofibroblastic phenotype of NCFs as observed at the protein level for FAP and αSMA." (PMID 34066976, 2021). "The gene expression of multiple inflammatory markers in the heart was significantly upregulated in tumor-bearing mice as compared to tumor-free mice, including the pro-inflammatory cytokines IL-1α, IL-1β, IL-6, and TNF- α and the inflammatory chemokines Mcp-1, Cxcl1, and Cxcl10." (PMID 34445729, 2021). "Interestingly, IL-1β is recognized as one of the most crucial cytokines in immunological regulation during tumour formation." (PMID 33658555, 2021).